STAT1 (signal transducer and activator of transcription 1)
Diseases named in the same sentence as STAT1 in open-access papers (continued):
Sharing a sentence is not in itself a finding about the gene and the disease.
infection (continued). "The data also showed that STAT1-dependent responses are not required to protect mice from lethal infection with all strains of MNV." (PMID 24225497, 2014). "Western blot analysis confirmed that infection with 5 m.o.i. of both H7 (FPV) and H5 (KAN-1) subtype viruses resulted in the activation of p38 (lanes 3 and 4), which occurred simultaneously with the phosphorylation of STAT1 at Ser727." (PMID 24189062, 2014). "Interestingly, infection of immunocompetent mice showed that all animals had long-term persistence of MNV-O7, whilst resolution and clearance occurred in 50 % of Stat1−/− mice." (PMID 24225497, 2014). "STAT-1 inhibition had no influence during infection alone, but it completely prevented the increase in acidification and association with BCG mediated by IL-12 and sIL-27R compared to the control group (no inhibitor)." (PMID 24618498, 2014). "Although the STAT-1 levels did not decline during the course of infection, a reduction in pSTAT-1 levels was observed from between 12 and 24 hpi." (PMID 23506210, 2013). "Infection with another type III strain (CTG) resulted in sustained STAT1 activation (data not shown)." (PMID 23527309, 2013). "The phosphorylation levels of STAT-1 serine 727 in the HLA-A2-transfected cells and in the mock cells were close to equal before infection (data not shown)." (PMID 23349666, 2013). "From these results, we conclude that a soluble, secreted factor arising from infection is not involved in parasite-triggered STAT1 activation." (PMID 23527309, 2013). "Unexpectedly, infection with Toxoplasma alone also induced phosphorylation and nuclear translocation of STAT1, independent of strain type." (PMID 23527309, 2013). "We hypothesized that feeding H. marginatum nymphs on STAT-1 KO mice will ensure that the tick is exposed to high levels of CCHFV during feeding, and therefore, result in a reliable infection of the tick with the virus." (PMID 23971007, 2013). "Increased sensitivity to infection was seen when myeloid cells lacked Stat1, whereas CD11cCreStat1flfl animals behaved similar to WT." (PMID 22719255, 2012). "STAT1 is integral to JAK/STAT signaling triggered by Type I and II IFN and upregulates a number of ISGs that are involved with the host defense against pathogen infection." (PMID 23006927, 2012). "Mice lacking Stat1 in T cells had the highest numbers of circulating immune cells in their blood 72 h after infection." (PMID 22719255, 2012). "Our data showed that caspase 3 cleavage was induced only in the liver of infected-wild type but not -STAT1 KO mice at day 1 after infection." (PMID 23050007, 2012). "It was previously shown that infection with a Pru(II) strain of Toxoplasma does not interfere with IFNγ induced serine phosphorylation of STAT1 in HFFs, but this has not been shown for any type I or III strains." (PMID 23240025, 2012). "After two hours of infection with either RH or RHΔrop16 parasites, HFFs were subsequently stimulated with IFNγ for two hours, cells were fixed and permeabilized, and IRF1 expression and STAT1 tyrosine phosphorylation were visualized." (PMID 23240025, 2012). "IFN treatment led to STAT1 phosphorylation that was not affected by infection with Candid#1 strain of JUNV in Vero cells." (PMID 22629479, 2012). "In summary, our findings indicate that HPIV1 infection did not lead to Stat1/2 degradation and that phosphorylation of Stat1 and Stat2 was reduced in WT HPIV1- and F170S HPIV1-infected cells following stimulation with IFN-α and IFN-β." (PMID 22355301, 2012). "The infection of Colo-679 cells with delNS1 or delNS1-IL15 did not induce STAT1 and STAT2 phosphorylation or MxA expression indicating a lack of interferon signalling." (PMID 22563505, 2012). "However, despite similar levels of viremia detected in both strains at 24 hours post-infection, IFN-α in STAT1−/− mice remained elevated but in STAT1−/−/2−/− mice it decreased to the level at or below the limit of detection (p<0.0001)." (PMID 21379341, 2011).
infection (continued). "At 6 h p.i., IFN-β-induced STAT1 phosphorylation in the nuclear compartment was not significantly affected by hMPV infection." (PMID 21949722, 2011). "Adult, immunocompetent wild-type mice are not susceptible to wild-type filovirus infection; however, inhibition of type I IFN (via knockout of the IFN alpha/beta receptor I, STAT1, or antibody-mediated depletion of IFN alpha and IFN beta) results in lethal infection with most wild-type filoviruses." (PMID 21994766, 2011). "However, when LGTV infection occurred prior to IFN addition, phosphorylation of STAT1, STAT2, Tyk2, and Jak1 were all inhibited, suggesting that LGTV must establish a productive infection to counteract the IFN response." (PMID 21994750, 2011). "However, by 24 hours post-infection, the gene induction levels observed in wild type and STAT1−/− mice were similar (<2-fold) except for the highly elevated Oas1a gene in STAT1−/− mice." (PMID 21379341, 2011). "Viral burden in STAT1−/−/AR−/− mice was equivalent to STAT1−/−/2−/− mice in all tissues at 72 hours post-infection (data not shown)." (PMID 21379341, 2011). "At day 2 post-infection with rMA15 virus, lung lesions in STAT1−/− mice were indistinguishable from those seen in 129 WT, IFNAR1−/− and IFNGR−/− infected animals." (PMID 20386712, 2010). "While STAT1−/− infected mice showed a similar trend of increased transcript levels at day 2, expression levels of IFNγ and MCP1 continued to increase through day 9 post-infection." (PMID 20386712, 2010). "In contrast to the results from IFN receptor knockout mice, previous studies have suggested that STAT1 −/− mice do not clear the Urbani virus by day 22 post-infection." (PMID 20386712, 2010). "Analysis of T cell responses revealed that STAT1 was not required for the development of a Th1 response, but was required for the infection-induced up-regulation of T-bet." (PMID 20368974, 2010). "Please note that a single non-infected cell in the ZEBOV infection panel showed nuclear accumulation of STAT1." (PMID 20084112, 2010). "Our working model is that upon infection of cells in an IFN-induced antiviral state, although virus transcription and protein synthesis are initially severely affected, PIV5 targets STAT1 for proteasome-mediated degradation." (PMID 19458173, 2009). "Taken together the data indicate that in the absence of SOCS-3, infection leads to a stronger activation of STAT1, resulting in enhanced expression of ISGs and reduced virus titers." (PMID 18989459, 2008). "On the contrary, the phosphorylated forms of STAT1 and STAT2 that were induced by MPRV infection could still be detected more than 24 h p.i., which would seem to suggest that these forms are stabilized in MPRV-infected cells." (PMID 17325370, 2007). "In addition, it appeared that the phosphorylated forms of both STAT1 and STAT2 were stabilized in MPRV-infected cells, as they were still detectable after 24 h infection." (PMID 17325370, 2007). "Again, some IFN seemed to have been induced following infection as STAT1 was phosphorylated in MPRV-infected cells in the absence of exogenous IFN." (PMID 17325370, 2007). "Given that STAT1 and JAK2 were significantly downregulated in infected cells in ADE compared to conventional infection conditions, it is possible that in ADE-mediated infection, these interactions are differentially modulated such that they further enhance viral evasion strategies." (PMID 39902963, 2025). "Interestingly, the differences in the balance between STAT1 and STAT3 involvement were also apparent ex vivo as we observed an age-dependent gradual decline in the ratio of STAT1/STAT3 transcription for infection-induced (expanded) CD4+ T cells as well as B cell populations." (PMID 40834853, 2025). "Interestingly, a similar level of induction of total STAT1, P-STAT1 (Y701), and MX1 was observed even in uninfected SUIT-2 (but not in MIA PaCa-2) in response to siMETTL3 treatment (“SUIT-2, mock-infection, siSCR” vs “SUIT-2, mock-infection, siMETTL3”)." (PMID 40214229, 2025).
infection (continued). "Since after suppression of host IFN responses (IAV vs IAVdNS1 infection and pretreatment with ruxolitinib before SARS-CoV-2 infection) there was a significant decrease in STAT1 upregulation as well as VILMIR upregulation, we predicted that VILMIR may be regulated by STAT1." (PMID 40130878, 2025). "We next tested the JAK1/2 inhibitor ruxolitinib, which acts upstream of STAT1 and is broadly effective at preventing IFN (and another cytokine) signaling, and again observed that JAK1/2 inhibition did not rescue the infection defect associated with p38β knockdown." (PMID 37345956, 2023). "Control unligated mouse carotid arteries and carotid arteries 7 days after ligation exhibited comparable levels of total STAT-1 positive cells, and infection with Ad: PRH S163C:S177C did not significantly affect the levels of STAT-1–positive cells compared to Ad: control arteries (n=4–5)." (PMID 36700427, 2023). "Furthermore, the restriction of VSV-GFP infection by MX1 is enhanced by additional, STAT1-dependent factors likely elicited by IFN production, further highlighting the utility of a STAT1-deficient screening platform for assessing the antiviral activity of individual ISGs." (PMID 35421191, 2022). "We observed that while 98% of WT microglia expressed MHC II at 12 days post-infection (DPI), 18% of microglia from MGSTAT1Δ mice were MHC II+ at this time point, allowing us to use MHC II expression in microglia as a reliable readout for STAT1 excision across experiments." (PMID 36067217, 2022). "Following infection of an IFN-activated cell, P protein concentration will initially be limiting, so high-affinity binding to a minor but critical pY-STAT1 subpopulation of cellular STAT1 may ‘gain a foothold’ in immune subversion until increased P protein expression permits more broad antagonism." (PMID 35576230, 2022). "Furthermore, CPIV3 infection significantly inhibited the transcription of the ISGs (RSAD2 and STAT1) in poly(I:C)-stimulated cells, which both implied that CPIV3 infections have evolved efficient strategies to antagonize the induction of endogenous type I IFNs." (PMID 35632770, 2022). "In addition, when compared to co-incubation with the inhibitor alone, the infection rate of either JAK1 or STAT1 inhibitor treatment was significantly higher without RNase 7 pretreatment (p < 0.01, compared to AMP plus JAK1 or STAT1 inhibitor treatment, respectively)." (PMID 35563546, 2022). "Infection-induced gene expression levels of inflammatory cytokines such as Il6 and Tnf, type I (Ifna4 and Ifnb), and type III IFNs (Ifnl2/3) as well as ISGs such as Mx1, Isg15, and Stat1 peaked simultaneously with peak viral loads on day 2 p.i. in lungs and upper airways." (PMID 36129445, 2022). "Stat1-knock-out (KO) mice are susceptible to lethal disease after LASV infection while immunocompetent inbred mice infected with LASV do not show any symptoms and efficiently clear the infection." (PMID 35605008, 2022). "Thus, FACS analysis confirmed our results for viral replication and viral mRNA expression, suggesting that STAT1 contributes to the resistance of WT macrophages to HSV-1 replication but not infection." (PMID 34653236, 2021). "In addition, our results in vivo showed that virulence of ΔNS1 mCherry was also reduced in STAT1−/− C57BL/6 mice as compared with animals infected with WT mCherry, where ΔNS1 mCherry was cleared four days after infection, while high levels of replication for WT mCherry were observed." (PMID 33920517, 2021). "Interestingly, both STAT1 and STAT2 degradation are less pronounced during NH/P68 infection, which could help to explain at least in part the low virulence pattern observed in pigs after infection with this attenuated ASFV strain." (PMID 34512601, 2021).
infection (continued). "Here, our new data confirm the detrimental role of M2 macrophages in this infection, since the lack of recruitment of CD11b+Ly6hiCCR2+PDL-1+ monocytes in STAT1−/− mice impairs the development of M2 macrophages at the site of infection and favors the elimination of the parasite." (PMID 34684235, 2021). "Moreover, STAT1 signaling, which is an important regulator of IFN-γ signaling, was significantly blocked (p < 0.01) by C. parvum in the mice of the Inf.Unt group at day 5 and 15 post-infection compared with the NC, Inf.Par, Inf.Chit, and Uni.Chit groups." (PMID 35095858, 2021). "To determine if the observed reduction in infection with RARRES3 overexpression might also be due to induction of interferon expression and downstream ISG induction, we used CRISPR/Cas9-mediated gene editing to generate a STAT1−/− A549 cell line." (PMID 34871166, 2021). "We next tested whether CR6 virus passaged intracranially in Stat1-/- mice had acquired the capacity to cause lethality in Stat1-/- mice when administered orally, a phenotype observed with CW3 but not CR6 infection." (PMID 33705489, 2021). "Similarly to that with NoV infection of Rag1−/− mice, vsiRNAs were undetectable by Northern blotting in NoV-infected Stat1/2−/− mice." (PMID 32753500, 2020). "In consequence, the higher phosphorylated/unphosphorylated ratio of STAT1 promoted by nsp3 in IFN-γ-stimulated macrophages might lead to more SARS-CoV-2 receptors being expressed at the surface of bystander epithelial cells, enhancing the infection process." (PMID 32549200, 2020). "However, in our study, increased viral RNA levels in STAT1/RAG DKO mice compared with the RAG1 KO mice in the early days of infection suggests that in RAG1 KO mice, there is STAT1-dependent, likely IFN-I-dependent, robust, early restriction of viral replication." (PMID 32310998, 2020). "In contrast to WT mice, where the CD8+ T cell response mediates clearance of LCMV following IP infection or causes LCM following IC infection, these cells are not critically involved in the immunopathology and weight loss observed in LCMV-Arm-infected STAT1-deficient mice." (PMID 30791575, 2019). "While MNV-induced diarrheic responses were not affected, Stat1-/- mice additionally lacking either Nlrp3 or GSDMD displayed lower levels of the fecal inflammatory marker Lipocalin-2 as well as delayed lethality after gastrointestinal MNV infection." (PMID 31017981, 2019). "However, MEKi did not increase the expression of STAT1 following RSVA2 infection (lane 6 vs lane 5), which is line with other induced ISGs." (PMID 31319869, 2019). "Similarly, infection with either AdGFP or OAdmCherry induced STAT1 phosphorylation in 231/pS cells but not in 231/pR cells." (PMID 31100952, 2019). "Together, from STAT1 and STAT2 germ-line mutation studies, it can be concluded that well-balanced and strictly controlled IFN-I and/or IFN-II-mediated immune responses are necessary but not sufficient to fight with infection." (PMID 29892288, 2018). "Infection with M. bovis BCG does not inhibit type I IFN-stimulated tyrosine phosphorylation of STAT-1, formation of homodimers, or transcription of genes regulated by STAT-1 homodimers, suggesting that inhibition of the response to type I IFN is related to the pathogenicity of Mtb." (PMID 29258190, 2017). "Noticeably, STAT1/STAT2 and IRF9 form a transcriptional complex upon activation of type 1 IFN receptors; this complex can subsequently translocate to the nucleus and induce the expression of a broad spectrum of IFN-stimulated genes that serve to contain infection." (PMID 29084769, 2017). "Since we did not observe any substantial decrease in the phosphorylation of STAT1 after 1 h infection with either WT-MYXV or M029-minus viruses, but inhibition of STAT1 activation is robust by 6 hpi, this suggests that for MYXV the viral phosphatase may not be encapsidated within the virion." (PMID 28157174, 2017).
infection (continued). "However, future studies will examine the cytokine expression profile over the course of infection in CD46+ pups, which may provide an explanation as to the reduction in STAT1 and STAT2 signaling by 10 dpi." (PMID 27178303, 2016). "A intense band of STAT-1 and a weak band of RIG-I appeared earlier at day 4 after the HEP-Flury infection, which indicated that the RIG-I-like receptor signaling pathway was activated quickly by HEP-Flury infection, this result was consistent with the results of RT-qPCR." (PMID 27242764, 2016). "We found that phosphorylation of STAT1 in infected cells was dramatically inhibited at later stages of infection (after 15 h p.i.), while no significant decrease in STAT1 phosphorylation was observed in the cells treated with corresponding culture supernatants (SN) from the infected cells." (PMID 24391501, 2014). "Furthermore, we observed that in HLA-B27-expressing cells the PKR inhibitor did not significantly inhibit STAT-1 serine 727 phosphorylation 2 hours after infection, whereas a clear inhibition was observed in mock cells." (PMID 23349666, 2013). "In fact, our data demonstrated that the reduced replication of influenza virus in the presence of meth was likely not caused by the enhancement of infection-induced IFN responses, since the levels of STAT1, phospho-STAT1, and MxA closely correlated with the levels of influenza virus replication." (PMID 23139774, 2012). "These reporter experiments also confirmed that while ROP16 can activate the tyrosine phosphorylation and nuclear translocation of STAT1, this STAT1 is not transcriptionally active; infection of this cell line with any of these strains did not result in the induction of luciferase." (PMID 23240025, 2012). "Investigation of the ability of anti-CLEC5A mAb to protect Stat1−/− mice from JEV-induced lethality revealed that 50% of Stat1−/− mice that succumbed to JEV infection died in the early stages (6 days post infection), and all the mice died within 9 days post infection." (PMID 22536153, 2012). "However, IL13RA, IL3RA, IL4, STAT1, STAT4 were down-regulated at this time point of infection." (PMID 21439068, 2011). "However, the mechanism leading to impaired STAT1 phosphorylation by hMPV infection was not identified." (PMID 21949722, 2011). "Following intravenous infection with 1010 GE of S221, 100% of STAT1−/−/AR−/− mice developed early lethal disease, whereas none of the STAT1−/−/GR−/− mice succumbed to infection, demonstrating that the survival phenotype of STAT1−/−/AR−/− mice recapitulates that of STAT1−/−/2−/− mice." (PMID 21379341, 2011). "Surprisingly, even though the infections were performed in the absence of IFNγ and thus under conditions where Stat1 should be inactive, survival of both wild-type and lpg− promastigotes was increased in Stat1−/− PEMs by more than twofold." (PMID 19381261, 2009). "In fact, infection of BHK cells with hPIV2 led to the specific degradation of STAT1 and not STAT2." (PMID 21994561, 2009). "Following on above findings, the authors sought to explore whether observed effects in IFN-γ-biased NHBE cells on mICAM-1 levels during HRV-14 infection could be mediated via a JAK/STAT signalling pathway; STAT-1 being a well-known signal transducer activated by IFN-γ." (PMID 18534017, 2008). "Indeed, transcripts of STAT-1, a key actor of this pathway, were drastically down-regulated at 24 h after infection, though there is no external activation by IFNγ." (PMID 18495030, 2008). "After IFN stimulation, a doublet band corresponding to phosphorylated STAT1α and STAT1β was detected both in uninfected and infected cell lysates, indicating that Tyr-phosphorylation of STAT1 was not inhibited by any of the MPRV proteins expressed during infection." (PMID 17325370, 2007).